FLNC (filamin C)
Diseases named in the same sentence as FLNC in open-access papers (continued):
Sharing a sentence is not in itself a finding about the gene and the disease.
cardiomyopathy (continued). "We reidentified all five loci harboring Mendelian cardiomyopathy-linked genes found in prior common variant analyses of DCM (ALPK3, BAG3, FLNC, PLEKHM2, and TTN)." (PMID 32382064, 2020). "Heterozygous mutations in the human filamin C gene (FLNC) located on chromosome 7q32 cause hereditary and sporadic myopathies and cardiomyopathies with marked phenotypic variability." (PMID 32887649, 2020). "While Filamin C is now recognised as an important disease gene for cardiomyopathies, future functional work, including the generation of model systems and organisms, is needed to gain insights into the detailed pathophysiology of cardiomyopathies." (PMID 29119312, 2017). "Concealed cardiomyopathy in the absence of echocardiographic observation is typical of certain sarcomeric mutations like Filamin C (FLNC) or Desmoplakin (DSP)." (PMID 40429571, 2025). "Furthermore, rare variants in cardiomyopathy genes, including TTN, MYBPC3, BAG3, and FLNC, have been identified as significant contributors to high HF risk." (PMID 40725457, 2025). "However, subsequent high-throughput screening in cardiomyopathy cohorts revealed a prominent role for FLNC in isolated DCM." (PMID 41440871, 2025). "The primary mechanisms underlying FLNC-associated cardiomyopathies are protein aggregation from non-truncating mutations and haploinsufficiency resulting from filamin C truncation." (PMID 38438525, 2024). "Our study raises the need for a better understanding of the role of FLNC in the regulation of calcium transport proteins in cardiomyocytes and consequently the pathogenesis of arrhythmias and reduced contractility in FLNC-related cardiomyopathy." (PMID 38334670, 2024). "ACM-causing mutations have also been identified in genes outside the desmosome, including phospholamban (PLN), filamin C (FLNC), desmin (DES), titin (TTN), and lamin A/C (LMNA), which are linked with other cardiomyopathies, including DCM and neuromuscular cardiomyopathies." (PMID 38610600, 2024). "Likewise, abnormal protein handling and degradation plays an important role in cardiomyopathy development due to mutations in genes such as BAG3 and FLNC." (PMID 37887855, 2023). "Secondly, the gene panel used in this study did not include recently established cardiomyopathy-associated gene such as filamin C (FLNC)." (PMID 37949661, 2023). "The recent association of MVP with pathogenic variants in several known cardiomyopathy genes, such as TTN (titin) and FLNC (filamin C) could explain disproportionate LV remodeling." (PMID 35498019, 2022). "The indication for primary prevention of sudden cardiac death in patients with HFimpEF is ambiguous, but ICD implantation should be considered in patients with an identified genetic cause of cardiomyopathy at high risk of ventricular arrhythmias (e.g., LMNA, SCN5A, FLNC)." (PMID 36103841, 2022). "Next, rare variant burden testing of 56 known cardiomyopathy genes demonstrated enrichment in MYH6 in 23 HLHS probands, 12 of whom had either a MYH6 variant co-segregating with familial CHD, compound heterozygosity, or synergistic heterozygosity with FLNC, which is also a cardiomyopathy gene." (PMID 35448093, 2022). "Consistently with other genetic variants found in cardiomyopathy, FLNC variants found in human DCM are not accompanied by concomitant myofibrillar myopathy." (PMID 35893404, 2022). "There is mixed evidence about the role of filamin C aggregation in cardiomyopathy." (PMID 33802723, 2021). "FLNC has been reported to correlate with cardiomyopathy 36, 37, but its role in melanoma is unknown." (PMID 33758620, 2021). "For several genes, especially FLNC, it is not clear why some truncating or missense variants cause pure myopathy while others cause cardiomyopathy without skeletal muscle involvement." (PMID 33802723, 2021).
cardiomyopathy (continued). "In our cohort, three patients had variants identified in genes (ABCC9, FLNC, MYBPC3) that have associations with different cardiomyopathies and may contribute to the clinical phenotype in these families." (PMID 33302605, 2020). "Given the relevance of cross-linkers in determining the physical properties of a cell, we hereby review the cases of inherited cardiomyopathies caused—or likely caused—by aberrant actin-binding and crosslinking proteins, namely alpha-actinin 2 (ACTN2), filamin C (FLNC) and dystrophin." (PMID 32824180, 2020). "We have demonstrated with the examples of Titin, FHL1, MLP/Csrp3, Filamin C and Phospholamban discussed here, that there are disease genes for cardiomyopathies beyond the “classical” genes coding for proteins with exclusively structural roles in the sarcomere or the cytoskeleton." (PMID 29119312, 2017). "In fact, during the enrollment period of this study new genes that were not included in the cardiomyopathy panels used, such as FLNC or FHL1, have been associated with HCM." (PMID 28771489, 2017). "The patho-mechanisms of Filamin C-related cardiomyopathies are less clear." (PMID 29119312, 2017). "However, the functional consequences of loss of filamins, especially filamin C, on integrin activation and its potential role in filamin C-related cardiomyopathy has not been explored in vivo." (PMID 36706168, 2023). "Interestingly, and consistent with other genetic variants found in cardiomyopathy, FLNC variants found in human DCM do not come along with concomitant myofibrillar myopathy." (PMID 33557094, 2021). "As FLNC mutations appear to predispose for arrhythmogenic events and sudden cardiac death in several cardiomyopathy entities, FLNC mutation might be an additional criteria for clinical decision making that favors early ICD implantation in cardiomyopathy." (PMID 33557094, 2021). "Hereby, we have reported what has already been discovered about ACTN2, FLNC and dystrophin in inherited cardiomyopathies and our effort might set the stage for broadening the panel of screened genes in cardiomyopathy patients by including the genes that code for other cytoskeletal cross-linkers." (PMID 32824180, 2020). "Three of the DCM-associated genes, FLNC, TTN (through its kinase activity) and cardiac specific FHOD3 encode maintenance partners of sarcomere and sarcomere-related structures, including Z-disk or F-actin myofibrils, which are disorganized or degraded in experimental models of cardiomyopathy." (PMID 28296976, 2017). "The research revealed that CNVs accounted for approximately 5% of 111 pediatric cardiomyopathy cases and included deletions in TTN and FLNC genes among patients with DCM." (PMID 40710783, 2025). "Thus, FLNC‐associated restrictive cardiomyopathy is mainly a consequence of intracellular protein aggregation due to dominant‐negative mutations, while dilated and arrhythmogenic cardiomyopathies result from the opposite mechanism of haploinsufficiency." (PMID 39315490, 2025). "Overall, lead variants at 9 of the 61 GWS loci were located nearest to known cardiomyopathy genes (ACTN2, ALPK3, BAG3, FLNC, PLN, TTN), representing significant enrichment (hypergeometric p = 6.01 × 10−11)." (PMID 36376295, 2022). "This pattern was commonly linked to desmosomal (DSP) and non-desmosomal (FLNC, LMNA) genes with both NDLVC and DCM and less often associated with ARVC, HCM, or other cardiomyopathies." (PMID 40238040, 2025). "In this review we discuss selected examples of cardiomyopathy genes (TTN, FHL1, CSRP3, FLNC and PLN) which, based on their known biological functions and the (limited) functional work on the disease-causing pathogenic variants, have been shown to have important signalling functions in the heart." (PMID 29119312, 2017).
cardiomyopathy (continued). "Advances in genetic characterization of cardiomyopathies have identified some desmosomal genes such as DSP and non-desmosomal genes such as Phospholamban, Filamin-C, and Transmembrane Protein 43, that are often associated with biventricular or LV-dominant subforms." (PMID 40021092, 2025).
myofibrillar myopathy (26 papers, 2015 to 2025). "FLNC, critical for muscle structure, is implicated in myofibrillar myopathy and isolated DCM (3–4% cases) with ventricular arrhythmias." (PMID 41440871, 2025). "Truncating variants in TTN are strongly associated with DCM, while mutations in DSP, LMNA, MYH7, RBM20, TNNT2, BAG3, and FLNC (the latter being linked to myofibrillar myopathy) are also commonly implicated." (PMID 39857686, 2025). "Mutations in FLNC, the gene coding for filamin C, causes myofibrillar myopathy (filaminopathy) characterized by disintegration of myofibrils predominantly at the Z-disc and massive protein aggregates in cytosolic deposits within the muscle fibers." (PMID 35846001, 2022). "It reported that FLNC (filamin C) mutations cause myofibrillar myopathies, and it was also associated with central nervous system disease such as Friedreich's ataxia, fragile X syndrome, and spinocerebellar atrophy." (PMID 34404444, 2021). "FLNC mutation was initially found to cause myopathy in a myofibrillar myopathy family, caused by a hotspot nonsense mutation p.W2710X." (PMID 30411535, 2018). "Careful clinical and family history, in many cases, will raise the suspicion of the underlying genetic cause of the disease, such as muscle weakness associated with FLNC missense variants causing myofibrillar myopathy, or reported consanguinity increasing the likelihood of recessive forms of HCM." (PMID 39132495, 2024). "In this study, we observed increased passive tension (PT) of skinned myofibers from patients with myofibrillar myopathy (MFM) caused by FLNC mutations (MFM-filaminopathy) and limb-girdle muscular dystrophy type-2A due to CAPN3 mutations (LGMD2A), compared to healthy control myofibers." (PMID 28915917, 2017). "In line with the expression pattern of FLNC, mutations identified in FLNC have been shown to be the underlying cause of different progressive muscular dystrophies, including distal and myofibrillar myopathy (DM and MFM, respectively), and hypertrophic cardiomyopathy (HCM)." (PMID 26555887, 2015). "FLNC may also play important roles in protein stabilization and degradation, as mutations in FLNC can cause myofibrillar myopathy characterized by disintegration of myofibrils, massive formation of protein aggregates, and altered degradation pathways within skeletal muscle fibers." (PMID 25861040, 2015). "Sequestration of FLNC or BAG3 has been proposed as a mechanism for myofibrillar myopathy whereby their accumulation depletes them from the Z-disc, compromising function and structural integrity in these fibres." (PMID 37427997, 2023). "Accordingly, acute and strenuous physical exercise has recently been shown to markedly accentuate the muscle fiber pathology in heterozygous W2711X filamin-C knock-in mice, which are a patient-mimicking model of filamin-C related myofibrillar myopathy." (PMID 27393313, 2016).
Ventricular arrhythmia (17 papers, 2017 to 2025). "Meanwhile, FLNC truncating variants have been found in overlapping DCM-ACM phenotypes characterized by frequent ventricular arrhythmias and skeletal muscle involvement." (PMID 40710799, 2025). "Mutations in genes such as LMNA, PLN, RBM20, and FLNC are associated with an increased risk of ventricular arrhythmias (VA) and SCD." (PMID 40711538, 2025). "Despite its low prevalence, DCM caused by truncating mutations in the FLNC gene often follows a more severe course, with higher risks of major ventricular arrhythmias (MVA), myocardial fibrosis, and SCD." (PMID 40524707, 2025). "Although truncating FLNC mutations are rare, they are associated with adverse outcomes, including major ventricular arrhythmias and sudden cardiac death." (PMID 40524707, 2025). "Variants in the FLNC gene have gained recognition due to their association with a higher risk of major ventricular arrhythmias and sudden cardiac death." (PMID 40524707, 2025). "Additionally, truncating variants in FLNC are implicated in myofibrillar disarray, skeletal muscle involvement, and recurrent ventricular arrhythmias, occasionally presenting with arrhythmic events that overlap with ACM." (PMID 40710799, 2025). "Truncating variants of FLNC are found in approximately 3 to 4% of patients with DCM which presents in early-to-mid adulthood and is associated with a high rate of ventricular arrhythmias and sudden cardiac death." (PMID 41440871, 2025). "Of the patients with diagnostic variants, 15.8% (81/514) had a variant in genes that have been associated with increased risk of ventricular arrhythmias (LMNA, RBM20, FLNC, and PLN)." (PMID 37795486, 2023). "Recent research have found that truncating variants in the gene-encoding filamin C (FLNCtv) are associated with arrhythmogenesis and DCM, with a reportedly high risk of ventricular arrhythmia." (PMID 35274013, 2022). "Such clinical features observed in FLNC truncating mutations were confirmed in another genetic study of 319 DCM families, which identified 13 FLNC truncation carriers, with 85% having either ventricular arrhythmias or sudden cardiac death." (PMID 33941202, 2021). "LMNA and SCN5A have long known to be associated with life-threatening ventricular arrhythmias, and the studies of RBM20, DSP, and FLNC discussed here clearly demonstrate significant arrhythmia and sudden death risks." (PMID 33040239, 2020). "New evidence indicates that loss-of-function mutations in filamin C (FLNC) contribute to DCM and portend high risk of ventricular arrhythmia." (PMID 33040239, 2020). "Furthermore, genetic testing has identified other DCM-causing genes including filamin C (FLNC) and RBM20 which may be associated with higher rates of ventricular arrhythmia." (PMID 31768884, 2019).
prostate carcinoma (14 papers, 2014 to 2025). A carcinoma that arises from epithelial cells of the prostate gland. "For example, in gastric and prostate cancers, FLNC was associated with increased invasiveness–FLNC knockdown enhanced cell migration/invasion, whereas restoring FLNC curbed these malignant behaviors." (PMID 41373405, 2025). "In line with our findings, FLNC has been proposed to be associated with poor prognosis in glioblastoma, esophageal squamous cell carcinoma, and prostate cancer." (PMID 33934493, 2021). "High filamin C associated with better prognosis of prostate cancer, leukemia and breast cancer patients." (PMID 25577646, 2015). "The CpG island of filamin C gene is also found to be hypermethylated in prostate cancer and associated with the systematic relapse of prostate cancer." (PMID 25577646, 2015). "Both EEF2 and FLNC were associated with the formation of prostate cancer." (PMID 34437425, 2021). "However, high expression of filamin C was found to be associated with better prognosis of prostate cancer patients (Log-rank test, p = 0.0024)." (PMID 25577646, 2015). "Through literature review, we found that in prostate cancer and non-small cell lung cancer, patients with high FLNC expression also showed poor prognosis." (PMID 40672387, 2025). "Through the application of bioinformatics technology, we identified the potential key genes associated with the occurrence and development of prostate cancer as FGF2, FLNA, VCL, FLNC, CAV1, ACTC1, and MYLK." (PMID 32547947, 2020). "Currently, quantitative proteomics has identified VCL and FLNC as two potential prognostic biomarkers and therapeutic targets for prostate cancer cell migration." (PMID 32547947, 2020). "Our clinical data is similar to results observed for FLNC expression in glioma tissues, but differs from those observed in prostate cancer, breast cancer, and leukemia." (PMID 28031525, 2017). "The prostate cancer cell line DU145 has a relatively high level of filamin C expression, which is comparable to that in the normal gastric cells GES-1." (PMID 25577646, 2015). "To answer this question, we performed gene silencing and overexpression analyses of filamin C in GC and prostate cancer cell lines." (PMID 25577646, 2015). "Silencing of filamin C in GC or prostate cancer cell lines enhanced cell migration and invasion, whereas filamin C overexpression inhibited the migration and invasion of cancers cells." (PMID 25577646, 2015). "Reduced expression of filamin C was also observed in 11 independent datasets of 561 cases of prostate cancer." (PMID 25577646, 2015). "Silencing of filamin C increased the expression of matrix metallopeptidase 2 and improved the metastasis of prostate cancer in a zebrafish model." (PMID 25577646, 2015). "Downregulation of filamin C was detected in primary and metastatic tumor tissues of GC and prostate cancers." (PMID 25577646, 2015). "Our results suggest that filamin C is a tumor suppressor involved in the development of GC and prostate cancer." (PMID 25577646, 2015). "The most interesting ones appeared to be claudin 3 (CLDN3) and alpha-methysacyl-CoA racemase highly expressed in prostate cancer and filamin C (FLNC) and keratin 5 with highest expression in normal prostate tissue." (PMID 24477410, 2014). "Interestingly, the opposite has been reported for gastric and prostate cancer cells, where FLNC expression inhibited cell migration and invasion." (PMID 28031525, 2017). "Furthermore, silencing of filamin C significantly increased the migration and invasion of prostate cancer cells." (PMID 25577646, 2015). "In addition, silencing of endogenous filamin C using short hairpin RNAs (shRNAs) significantly improved the proliferation of prostate cancer cell line DU145 that expresses relatively high level of filamin C (p = 0.009 for sh1 and p = 0.0002 for sh4)." (PMID 25577646, 2015). "Reduced expression of filamin C has also been observed in the metastatic tumor of prostate cancer." (PMID 25577646, 2015).
prostate carcinoma (continued). "Furthermore, filamin C mRNA is reduced in the metastatic tissues of squamous cell carcinoma and prostate cancer." (PMID 25577646, 2015). "In addition, methylation of the filamin C promoter is also found in prostate cancer, ovarian cancer, and colon cancer." (PMID 25577646, 2015). "Similarly, partial silencing of filamin C considerably increased the migration of prostate cancer cell line PC-3 (p = 0.021)." (PMID 25577646, 2015). "Filamin C (FLNC, selected in all of the 20 folds) is a large actin-cross-linking protein which has been shown to inhibit proliferation and metastasis in gastric and prostate cancer cell lines." (PMID 28650955, 2017).